IL10 (interleukin 10)
Diseases named in the same sentence as IL10 in open-access papers (continued):
Sharing a sentence is not in itself a finding about the gene and the disease.
tumor (continued). "Tumor-induced systemic inflammation promotes tumorigenesis, invasion, and metastasis via inflammatory mediators, such as tumor necrosis factor-alpha, interleukin-6, and interleukin-10." (PMID 35410196, 2022). "Increased IL10 in the proximal segments of the colon of DMH-rats with proximal tumor location indicated that IL10 could play an important role in regulating the barrier properties in this colon segment." (PMID 36555251, 2022). "However, IgA can be associated with specific B cell subsets and their regulatory functions, such as the production of immunosuppressive cytokines like IL-10, which can support a pro-tumour microenvironment." (PMID 35380164, 2022). "In addition, Tregs promote tumour angiogenesis in the TME through the secretion of VEGF‐A and IL‐10, thereby supporting tumour metastasis." (PMID 35969010, 2022). "Treatment with 5-aza-dC and TSA synergistically decreased the mRNA levels of M2 cytokines (il-10, il-4, and tgfb) and a marker (arg1) in tumor tissues, while increasing those of M1 cytokines (il-12p40 and ifng) in tumor tissues, as compared to either therapy alone and in the saline-treated control." (PMID 36483544, 2022). "Accordingly, any drug combinations that could reduce the levels of TGF-β, IL-10, and Foxp3 and increase the level of IFNγ, would have a potent inhibitory effect on tumor growth." (PMID 36544523, 2022). "Since the tumor microenvironment is abundant in anti-inflammatory cytokines such as IL-10 and TGF-β, the use of armed viral vectors can reverse this profile and restrict the expression of appropriately chosen cytokines, to favor a less immunosuppressive context." (PMID 35495634, 2022). "Also, tumor cells produce C5a, which in turn increases the release of IL-10, transforming growth factor-beta (TGF-β1) and monocyte chemoattractant protein-1 (MCP-1), thus enhancing tumor metastasis." (PMID 35173724, 2022). "In addition, HCMV gene products and proteins have been detected in GBM tumors and various studies indicate that many viral genes products can be implicated in tumor malignity, including HCMV IL-10." (PMID 36441804, 2022). "MDSCs also express suppressive cytokines like TGF-β and IL-10 in the tumor." (PMID 35197076, 2022). "A high concentration of interleukin 10 (IL-10) is another common phenomenon in tumours." (PMID 35806034, 2022). "Furthermore, we found that IL-10 expression is higher in Tr1 cells than in cTreg cells in tumor mice, reaching the highest frequencies in TILs." (PMID 35860556, 2022). "In addition, we found that interactions between fibroblasts and immune cells through the IL-10 signaling pathway were significantly increased in the tumor microenvironment in patients with high MOXD1 expression compared with patients with low MOXD1 expression." (PMID 36620542, 2022). "In contrast to tumor‐associated macrophages, we did not detect changes in IL‐10 and TGF‐β production by NRP2‐deficient AM exposed to apoptotic cells, suggesting that NRP2 does not regulate the expression of these immunosuppressive cytokines in AM." (PMID 34861108, 2022). "These APCs inhibit T-cell activation by expressing PD-L1 and by establishing interactions with PD-1 on T cells, and concurrently, they can secrete a substantial number of cytokines such as IFN-γ, IL-2 and IL-10, which indirectly promote PD-L1 expression in tumor cells and APCs41–43." (PMID 35165282, 2022). "In patient tissues, expression of IgG4 correlates with CD20 and tumor expression of IL-10." (PMID 35255925, 2022). "IL-10 has growth factor-like effects on tumor cells, and IFN has obvious cytotoxic effects." (PMID 35419003, 2022). "Thus, to study IL10 signaling in macrophage promotion of tumor cell transendothelial migration, eTEM assays were used with BMDMs with and without a neutralizing antibody for the IL10 receptor." (PMID 36077870, 2022).
tumor (continued). "Additionally, d-MAPPS reduced percentage of tolerogenic, IL-10-producing DCs in the tumors (p < 0.001) preventing tumor cell-driven generation of immunosuppressive microenvironment." (PMID 35757015, 2022). "Furthermore, the splenocytes from T-01-treated mice showed increased secretion of the immune-enhancing cytokines INF-γ, IL-2, and IL-4 and decreased secretion of tumor-suppressive IL-10." (PMID 35615265, 2022). "Non-resident macrophages, such as tumor-associated macrophages (TAMs), induce immune tolerance against tumors by producing high levels of IL-10 and increasing the expression of PD-L1, thus limiting the immune response of T cells to cancer cells." (PMID 36532044, 2022). "These peptides were able to increase the survival time of TC-1 tumor-bearing mice after therapeutic vaccination with an HPV16E7 peptide-based vaccine containing IL-10 inhibitor via increased recruitment of T cells to the tumor site, probably by TC-1-promoted secretion of proinflammatory IL-6." (PMID 35445137, 2022). "Mast cells may promote tumor growth through the release of pro-angiogenic factors, the release of proteases able to affect stromal composition, and the release of tumor-promoting cytokines, including IL-10 and TGFβ." (PMID 36313712, 2022). "Moreover, hypoxic tumor cell-released autophagosomes from human hepatocellular carcinoma cell line HepG2 induce more IL-10-producing B cells, with suppressive functions on CD4+ and CD8+ T cells." (PMID 36233088, 2022). "Furthermore, injection of PEGylated IL-10 into MMTV/HER2 transgenic mice led to tumor rejection that was dependent on activated CD8 T cells in an IFN-γ and Granzyme B-dependent manner." (PMID 34769278, 2021). "Further support for the immunostimulatory role of IL-10 comes from studies in rodent tumour models where IL-10 administration promotes proliferation and expansion of tumor-resident cytotoxic CD8+ T cells as well as IFNγ production, thereby enhancing antitumor activity." (PMID 34234779, 2021). "Finally, we sought to comprehensively evaluate the effects of IL-10 on the tumor microenvironment (TME) with a murine IL-10 based CAR-T in an immunocompetent MLL-AF9 model." (PMID 34392305, 2021). "Immunosuppressive IL-10+ B cells may accumulate at inflammatory or tumor sites through increased cell survival via the enhanced expression of transcription factor C-MAF upon restraint of SLAMF5 receptor-mediated signaling." (PMID 34359321, 2021). "Additionally, in the tumor microenvironment, the secretion of proinflammatory cytokine IL-6 increased, while the secretion of immunosuppressive cytokine IL-10 was downregulated." (PMID 34575449, 2021). "The suppressive cytokine IL-10 is a potential target to elicit a robust anti-tumor immunity." (PMID 34489941, 2021). "Tumor-associated macrophages (TAMs), which largely display an M2-phenotype, exhibit pro-tumorigenic functions and express CD206, programmed death-1 (PD-1) and its ligand (PD-L1), and IL-10." (PMID 35008514, 2021). "It was reported that CD163+ tumor-associated macrophages could inhibit T-cell proliferation and activation by secreting CCL22, IL-10, and TGF-β and recruiting regulatory T cells (Tregs) to tumor tissues." (PMID 35155189, 2021). "In addition, high levels of IL-10 in serum and the tumor microenvironment have often been correlated with a worse prognosis in solid neoplasms and hematological malignancies, including ALL." (PMID 34335758, 2021). "Importantly, the balance between IL-12 (which favors clearance) and IL-23, and to a lesser extent IL-10 (which favor tumor persistence), keeps tumors in equilibrium." (PMID 33807260, 2021). "In this work, we demonstrated that localized IL-10 could enhance oncolytic adenovirus viroimmunotherapy in immunocompetent murine tumor models." (PMID 33717103, 2021). "However, there is a population of regulatory B-cells (B-reg) that favor tumor development through IL-10, IL-35, TGF-β and IL-21 production, which prevent the expansion of proinflammatory cells." (PMID 33671415, 2021).
tumor (continued). "In our experiments, tumor cells inoculated with EVs-Hsp70 demonstrated significantly lower numbers of arginase-1-positive TAMs, that correlates with low concentrations of serum IL-10." (PMID 34716378, 2021). "Co-administration of IL-10 also reduces tumor Th17 numbers, and dramatically improves tumor burden." (PMID 34489941, 2021). "Likewise, EA reduced the expressions of IL-1β protein and TNF-α protein and increased the expression of IL-10 protein in tumor tissues." (PMID 35095910, 2021). "Similarly, the tmTNF-α antibody suppressed the production of proinflammatory mediators, promoted the release of IL-10, and inhibited the infiltration of macrophages, Treg cells, and MDSCs at the tumor stage." (PMID 34675913, 2021). "In addition, MSC-derived nanovesicles can upregulate the anti-inflammatory cytokine interleukin 10 (IL10), which has been reported to play a vital role in the control of skin wound inflammation and scar formation." (PMID 34567129, 2021). "The IL10+Ad-hTERT group, however, leaded to tumor stabilization or regression statistically." (PMID 33717103, 2021). "IL-10 can exert both tumor-promoting and -suppressive effects." (PMID 33578830, 2021). "In our study, IL10 appears to correlate with tumor burden and to decrease during the follow up." (PMID 35008292, 2021). "It has been reported that MDSCs can induce the expansion of Tregs and reduce the anti-tumour activity of effector T cells, while Tregs can regulate immunosuppression by secreting cytokines, such as IL10, IL35, and TGF-β, thereby suppressing the effector T-cell response." (PMID 35069558, 2021). "Interleukin-10 (IL-10) is a cytokine that can promote anti-tumor immunity." (PMID 34621543, 2021). "Moreover, tumor cells can release immune-suppressive cytokines (such as TGF-β, IL-10, etc.)and exosomes (containing miRNAs, lncRNAs, proteins, and so on) to affect anti-tumor immune responses." (PMID 33868274, 2021). "IL-10 is a homodimeric cytokine that is produced by various cell types including T cells, B cells, macrophages, mast cells, dendritic cells (DCs), granulocytes, and tumour cells." (PMID 33401460, 2021). "Furthermore, the IL-10+Ad-hTERT remedy showed significantly superior effects in reducing tumor volume and extending overall survival in these mice tumor models." (PMID 33717103, 2021). "Although I did not dissect the tumor microenvironment in this study, the suppressive effect of IL-10 on tumor associated macrophages does help to stop cancer progression." (PMID 33912464, 2021). "Moreover, a recent phase I clinical trial demonstrated that pegylated IL-10 in combination with anti-(α)PD-1 therapy elicited robust anti-tumour immune responses and an improvement in clinical outcomes in patients with renal and non-small-cell carcinoma." (PMID 33401460, 2021). "The existence of Breg is physiologically related to the immune tolerance crucial to restrain the development of autoimmunity, but in TME they are expanded and support tumor growth by secreting IL-10, IL-35 and TGF-β that impair T cell proliferation and induce Treg." (PMID 33920505, 2021). "My findings support the first hypothesis, wherein we demonstrate that IL-10 exhibits strong anti-tumor effects." (PMID 33912464, 2021). "Therefore, additional molecular insights into the role of IL-10 for tissue homeostasis both within and outside of the tumor are required." (PMID 34072260, 2021). "The signal transducer and activator of transcription factor 3 (STAT3) signalling pathway is upregulated in TAMs and is responsible for the production of tumor-promoting inflammatory molecules, such as IL-10 and IL-6, as well as inhibition of the tumor-suppressive inflammatory molecule TNF." (PMID 33766119, 2021).
tumor (continued). "Although type Th2-type cytokines such as IL-4, IL-5, IL-6, IL-10, and IL-13 are more involved in host anti-parasitic defense and allergic reactions, evidence suggests that they can elicit anti-tumor responses via eosinophils activation as well as stimulating antibody production." (PMID 34868907, 2021). "The recruitment of bone marrow-derived monocytes, which differentiate into TAMs, is driven by circulating mediators released by both tumor and stromal cells, including cytokines (IL-1β, IL-10, IL-13, IL-34), osteoactivin, VEGF-A, and colony stimulating factor-1 (CSF-1)." (PMID 33922362, 2021). "In these animal studies, IL-10 overexpression and exogenous IL-10 suppressed tumor development." (PMID 33578830, 2021). "Similarly, the DAMP, heat shock protein 70 (Hsp70) can prevent the translocation of peptide-major histocompatibility complexes (pMHC) and promote the production of interleukin 10 (IL-10), which subsequently suppresses anti-tumor T cell responses." (PMID 34187428, 2021). "Importantly, IL-10 derived from TAMs can also inhibit DC antigen presentation, further dampening tumor immunity (step 6)." (PMID 33968034, 2021). "The CNS is compatible with a plethora of immunosuppressive mechanisms to avoid damage caused by excessive immune responses, among which IL10, TGF-beta, VEGF, and COX are often hijacked by tumor cells to evade immune attack, leading to the extremely low response rate of GBM to ICB." (PMID 35111196, 2021). "Moreover, MDSCs can also secrete a series of cytokines, such as IL-10 and TGF-β, and present tumor-associated antigens, to induce the proliferation of Treg cells." (PMID 33986819, 2021). "CAFs also drive the recruitment of monocytes to the tumour site and their differentiation to the M2 macrophage phenotype which contribute to the tumour progression through secretion of pro‐inflammatory cytokines such as IL‐6, IL‐8, IL‐10 and TGF‐β." (PMID 33251764, 2021). "Previous studies have provided contradictory evidence about the anti-tumor effects of IL-10." (PMID 33912464, 2021). "In tumor models, these cells promote the growth of various tumors by suppressing immune systems or by exerting protumor activity through immuno-suppressive agents such as interleukin-10 (IL-10) and transforming growth factor-β (TGF-β)." (PMID 34500609, 2021). "This is because tumours release FTH1 to induce an immunosuppressive microenvironment by re-programming dendritic cells so they induce production of the anti-inflammatory cytokine IL-10 from regulatory T cells, hence, allowing the tumour to escape immune surveillance." (PMID 34211054, 2021). "Furthermore, in vitro co-culture models have shown that tumor cell-macrophage co-culture induced M2-like polarization via increased expression of IL-10, IL-12, IL-6, TNF-α, CCL5, CCL22, and CSF1." (PMID 34439281, 2021). "Tumor-infiltrating Tregs suppress proliferation of other effector T cell populations via contact-dependent mechanisms and contact-independent mechanism, primarily through IL-10 and TGF-β secretion." (PMID 33532902, 2021). "With the recruitment of immune suppressor cells, immunosuppressive molecules such as IL-10 and TGF-β secreted from these cells would also increase, which in turn induce more immune suppressor cells within tumor, finally forming a vicious circle that cause the acquired drug resistance." (PMID 34243757, 2021). "IL-10 induces anti-tumor actions by inhibiting angiogenesis and cell proliferation of PCa cells." (PMID 34604038, 2021). "Moreover, IL-10 has been considered one of the main culprits of inducing the immunosuppressive tumor microenvironment via pDCs." (PMID 33692796, 2021). "Moreover, tumor-derived exosomes not only release IL-10, but also upregulate microRNA-214 (miR-214)." (PMID 33532902, 2021). "Furthermore, in vitro knockdown of IL-10 switches latent EBV-infected tumor cells to the lytic form leading to tumor cell death." (PMID 34680337, 2021).
tumor (continued). "Another study confirmed these results by demonstrating an upregulation of lincRNA-p21 in TAMs, whereas knockdown facilitated macrophage polarization to M1 by upregulating TNF-α, IL-6, and iNOS, downregulating IL-10, IL-4, and Arg-1, and reducing tumor-cell proliferation and migration." (PMID 34439281, 2021). "In LLC xenograft mice, endostatin inhibited tumor angiogenesis by reducing the number of CD31+ cells and VEGF expression, aggravated hypoxia, and increased levels of inflammatory cytokines (IL-4, IL-6, IL-10) in tumor and CCL2 expression in endothelial cells and fibroblasts." (PMID 34209679, 2021). "Interestingly, some studies, however, report an increase in intra-tumoral cytotoxic CD8+ T cells upon IL-10 delivery to the tumor." (PMID 33936033, 2021). "IL‐10 could bind with IL‐10 receptors on tumor cells to activate STAT3, which thus promotes the proliferation of tumor cells via the activation of cell cycle‐related proteins." (PMID 34026610, 2021). "Given that IL-10 plays a dual role in tumor development, these results remain inconclusive." (PMID 34638991, 2021). "A previous study found that the anti-tumor effect of IL-10 is IFN-γ dependent." (PMID 33912464, 2021). "Additionally, it was shown that IL-10 was released by M2 macrophages and promoted tumor proliferation in vitro." (PMID 34654395, 2021). "It has been shown that tumor cells could induce the immature differentiation of DCs by reducing adhesion molecules or secreting immune inhibition cytokines, such as IL-10 and vascular endothelial growth factor (VEGF)." (PMID 34566989, 2021). "IL-10 is an immunosuppressive cytokine commonly expressed in NPC tumor cells." (PMID 33718235, 2021). "This was indicative of IL-10 with a combined effect of stimulatory cytokines like IL-2 and might trigger NK cell-mediated immunity against tumour cells." (PMID 34336101, 2021). "In addition, activation of A2A receptor signaling by adenosine enhances the release of important cytokines, such as VEGF, IL-6, IL-10, and TGFβ, which suppress the inflammatory response and enhance tumor survival." (PMID 35127700, 2021). "Furthermore, HCMV-infected cells can secrete a variety of cytokines (such as IL-10 and transforming growth factor-β), extracellular matrix proteins, and angiogenic factors to change the tumor microenvironment." (PMID 33959494, 2021). "Also, among tumor-infiltrating MDSCs, IL-10-releasing M-MDSC and G-MDSC were decreased in rSmeg-hMIF-hIL-7 compared with all other groups." (PMID 34389619, 2021). "Also, IFN production in tumor was upregulated and the amount of tumor‐derived factor interleukin‐10 (IL‐10) changed oppositely." (PMID 34026439, 2021). "Indeed, by inhibiting the signaling of the nuclear factor-κB (NF-κB) IL10 can have an anti-tumor effect, whilst by mediating immunosuppression, IL10 can allow cell maturation and differentiation and thereby promote cancer immune evasion." (PMID 34205944, 2021). "Tumor cells recruit neutrophils, macrophages, Tregs and immunosuppressive myeloid suppressor cells (MDSCs) in TME which produce factors such as TGF-β, IL-10, PD-1 and arginase to escape the immune responses providing a strong immunosuppressive environment for tumor growth." (PMID 34923966, 2021). "These evidences seem to indicate that elevated IL-6, IL-8 and IL-10 in non-tumor patients are common results of infections (including infections of different sites and different microorganisms), so our data does not support bacterial infections in the lungs The specificity." (PMID 34925324, 2021). "Tumor cells are known to overexpress key cytokines, such as IL-10." (PMID 33805488, 2021). "Furthermore, IL24 belongs to the IL10 gene family that possess antitumor properties including inhibition of tumor angiogenesis and induction of tumor cell apoptosis." (PMID 34771568, 2021). "A report has also shown that suppression of tumor cell killing T cells due to the release of IL-10 could lead to tumor growth." (PMID 35317109, 2021).